MMP2 (matrix metallopeptidase 2)
Diseases named in the same sentence as MMP2 in open-access papers (continued):
Sharing a sentence is not in itself a finding about the gene and the disease.
melanoma (continued). "The decrease of ARSB activity resulted in the overexpression of melanoma progression factors, such as chondroitin sulfate proteoglycan 4 (CSPG4) and pro-matrix metalloproteinase 2 (pro-MMP2), causing increased invasiveness of melanoma cells." (PMID 37601653, 2023). "In our study, we evaluated the prognostic value of MMP2 expression in melanoma, the OS of patients with high MMP2 expression was significantly lower than patients with low MMP2 expression, and this trend was more pronounced in patients with BRAF mutation." (PMID 36788565, 2023). "IL-23 generated by astrocytes was found to increase MMP2 secretion in brain metastatic melanoma cells, whereas inhibiting MMP2 expression decreased IL-23-induced migration, implying a link between the two." (PMID 37190188, 2023). "Further research suggested METTL3 accelerated invasion and migration of melanoma cells by upregulating matrix metallopeptidase 2 (MMP2)." (PMID 37124930, 2023). "Luteolin inhibited the proliferation and induced the apoptosis of melanoma cells by downregulating MMP-2 and MMP-9 expression through the PI3K/AKT pathway." (PMID 36829966, 2023). "The study also revealed that HPF treatment downregulated melanoma progression markers, such as CD133, OCT-4, AXL, uPAR, and MMP-2, which are associated with tumor growth, metastasis, and EMT." (PMID 37507910, 2023). "The overexpression of CSE1L causes melanoma cells (B16F10) to generate MPs, and the knockdown of CSE1L reduces v-H-Ras-induced MP formation, matrix metalloproteinase 2 (MMP2) and MMP9 secretion as well as metastasis." (PMID 37046617, 2023). "Subsequently, these researchers found that GA can hinder the invasiveness of melanoma cells by inhibiting MMP-2 through its involvement in the Ras and ERK signaling pathways." (PMID 37687080, 2023). "In vitro studies corroborating the expression of AnxA1 by melanoma cells is related to invasiveness behavior, depending, at least in part, on metalloproteinase-2 (MMP-2) expression." (PMID 36766767, 2023). "Phosphoinositide 3-kinase elevates the level of matrix metalloproteinase-14 (MMP-14) in aggressive cells; MMP-14 in turn activates MMP-2, which in turn activates the secretion of γ2′ and γ2x pro-migratory fragments leading to VM in melanomas." (PMID 36776217, 2023). "According to a mouse melanoma model, we found that MMP2 inhibitor synergistically with PD-1 antibody induces tumor regression, which dependent on decreased infiltration of CAFs." (PMID 36788565, 2023). "In a mouse model of melanoma, MMP2 inhibitor synergistically with PD-1 antibody induces tumor regression." (PMID 36788565, 2023). "MMP2 is secreted from melanoma cells and then cleaves IFNAR1, leading to inactivation of DCs, induction of T helper 2 (Th2) cell polarization and low levels of STAT1 phosphorylation." (PMID 36104718, 2022). "Both compounds 7 and 4 at 10 and 20 μM inhibited MMP2 gelatinase activity in the A375 melanoma cell line." (PMID 35163058, 2022). "VGVAPG increased the migration of melanoma cells and the generation of elastin-derived peptides, enhancing the expression of elastin-degrading MMP-2 and MMP-3 through binding to galectin-3 and EBP receptors." (PMID 35008401, 2022). "As a reaction to exogenous melanoma antigens, active MMP-2 promotes TH2 cell differentiation, degrades the IF-α/β receptor in immature DCs and increases the protein expression of OX40 ligand in mature DCs." (PMID 36776395, 2022). "Elastin fragments enhanced MMP-2 and MMP-14 production by melanoma cells that allowed further melanoma cell invasion through a type I collagen matrix by upregulating MMP-2 expression and activation." (PMID 35008401, 2022). "Aggressive melanoma phenotypes contribute to VM progression accompanied by the expression of molecular markers such as VE-cadherin and MMP2/9." (PMID 36401329, 2022). "For instance, melanoma cells significantly affect microglia morphology, proliferation, migration, and matrix metalloprotease (MMP)-2 activation." (PMID 36411434, 2022).
melanoma (continued). "The upregulation of MMP-2, with its membrane receptor at the leading front of the cell invadopodium, allows modulation of melanoma adhesion and spreading in an ECM environment." (PMID 36005056, 2022). "MMP-2 expression is also significantly increased in the tumour tissue of patients with melanoma at the primary and secondary sites." (PMID 36005056, 2022). "The combined effects of decline of ARSB and increase of C4S, CSPG4, and MMP2 significantly increased the invasiveness of the melanoma cells." (PMID 36361933, 2022). "MMP-2 upregulation has been detected in melanoma, breast, ovarian, pancreatic, prostate, and lung cancers, among others, and associates with metastasis or poor prognosis." (PMID 36559106, 2022). "Bcl-2 and Bcl-XL proteins were also found to cooperate with hypoxia to induce MMP-2 expression in melanoma." (PMID 36224457, 2022). "In human melanoma cells, expression of pro-MMP2 and MMP-9 was increased following ARSB silencing and was mediated by decline in SHP2 activity and increase in phospho-ERK1/2." (PMID 36361933, 2022). "In turn, microglial cells facilitate phenotypic changes in melanoma cells, resulting in increased proliferation, migration, and MMP-2 activation that promote their aggressiveness." (PMID 36411434, 2022). "MMP-2 was the only protease that was abundant in the conditioned media from all three melanoma lines and expressed at concentrations as high as 200–300 ng/mL in NZM7." (PMID 36005056, 2022). "MMP-2 mRNA and protein are expressed in human melanoma mouse xenografts and this expression positively correlates with melanoma aggressiveness." (PMID 36005056, 2022). "MMP-2 was added directly to the apical face of the endothelial cells to target the location where the melanoma cells would first make contact." (PMID 36005056, 2022). "When the cocultivation with melanoma cells was performed, MMP-2 expression by fibroblasts was increased." (PMID 34204372, 2021). "In melanoma, miR-4633-5p has been shown to act as a tumor suppressor gene, suppressing the activation of the Akt pathway and the secretion of MMP2; in contrast, consistently higher miR-4633-5p showed an association with advanced thyroid cancer staging." (PMID 34590612, 2021). "In accordance with this, elevated METTL3 expression was detected in human melanoma cell lines, which led to increased m6A activity, colony formation, and invasion of melanoma cells through MMP2 and N-cadherin accumulation." (PMID 35117988, 2021). "In the case of A2058 melanoma MMP-2 and MMP-9 expression was upregulated by various cytokines and inducers." (PMID 33732640, 2021). "MMP2 expression in melanoma promotes tumor growth in a TLR2- and TLR4-dependent manner that requires APCs and T cells." (PMID 34032639, 2021). "Because extracellular matrix components can shape the microenvironment, we investigated the role of matrix metalloproteinase 2 (MMP2) in melanoma tumorigenesis." (PMID 34032639, 2021). "Overexpression of mir-34a attenuates migration, invasion, and EMT by decreasing LGR4 expression, which regulates the expression of the matrix metalloproteinase 2 (MMP2) in melanoma cell lines." (PMID 33946652, 2021). "Microglia cells promote melanoma cell proliferation, migration, ability to penetrate the brain endothelium, ability to grow as spheroids in 3D cultures, and MMP‐2 activity." (PMID 33274599, 2021). "In summary, OE of Mmp2 in melanoma cells promotes tumor growth and depends upon the presence of cDC1s and lymphocytes as the absence of either of these cell populations abrogates the growth advantages." (PMID 34032639, 2021). "Lut exhibited a similar behavior in human melanoma cells (A375 cells), where it inhibits proliferation, induces apoptosis, and reduces the expression of MMP-2 and MMP-9 (in vitro and in vivo)." (PMID 33498927, 2021). "The chondroitin-4-sulfate chains of melanoma-specific CSPG bind to the C terminus of pro-MMP2 to facilitate its activation by membrane-bound MMP16." (PMID 33809973, 2021).
melanoma (continued). "Since matrix metalloproteinase-2/-9 (MMP-2/-9) are known to play an important role in melanoma metastasis, we estimated their enzymatic activity with gelatin zymography." (PMID 33833342, 2021). "In human melanoma cells, downregulation of DDR2 is associated with decreased MMP2 and MMP9 activities." (PMID 33917302, 2021). "In cancer including melanoma, MMPs like MMP2/7/9 facilitate invasion/metastasis and participate as regulators of tumor cell proliferation and apoptosis." (PMID 34360915, 2021). "MMP-2 upregulates vascular endothelial growth factor-A (VEGF-A) secretion by the tumor cells in human melanoma leading to the interaction of the melanoma cells with the lining of the blood vessels and favoring their extravasation." (PMID 34912809, 2021). "We also found that PLX treatment decreased the expression of integrin-α4, whereas it increased the levels of N-cadherin and MMP2 in the melanoma cells." (PMID 33810045, 2021). "In this context, OE of MMP2 in melanoma would be predicted to have deleterious outcomes on the immune system, in addition to promoting tumor growth and invasion through modulation of the stromal architecture." (PMID 34032639, 2021). "Using a 3D reconstructed human melanoma skin model, both untreated naïve and resistant melanoma cells had elevated levels of MMP2/9 and were highly invasive, but treatment with GANT61, which downregulated GLI1/2 expression, reversed these effects." (PMID 34572373, 2021). "The anti-metastatic action of Api was also found in human melanoma cells (A375 cells), where Api reduces the MMP-2 and MMP-9 in a dose-dependent manner." (PMID 33498927, 2021). "A similar phenomenon was observed in XBP1 overexpressed melanoma cells, wherein the increasing expression of XBP1 promotes melanoma cell proliferation by activating the AKT pathway associated with MMP2 and MMP9." (PMID 34484336, 2021). "Membrane type-1 MMP (MT1-MMP) (or MMP-14) is a cell–surface membrane protein, which activates MMP-2 leading to matrix degradation and melanoma cell invasion and metastasis." (PMID 34207884, 2021). "This is the case for HNK which down-regulates the expression of MMP-2 and -9 in A375 and B16 melanoma cells, so as to reduce the invasion/migration capacities of these tumor cells." (PMID 33534099, 2021). "For instance, the ‘writers’ METTL3 is upregulated and governs in invasion/migration through MMP2 in melanoma." (PMID 34446007, 2021). "Specifically, Schnaeker at al. found that melanoma cells contained cytoplasmic vesicles positive for MMP2 and MMP9 that were released via microtubules to induce tumor invasion." (PMID 34071761, 2021). "More recently, Balta and collaborators highlighted the existence of a link between L-plastin expression, total MMP activity and MMP-2 release in MV3 melanoma cells." (PMID 33618712, 2021). "IL-6 was known to activate STAT3 and consequently increase MMP-2 expression and the metastatic ability of cancer cells in malignant melanoma." (PMID 34267603, 2021). "Nonetheless, the growth and invasion of melanoma cells into the brain parenchyma relied primarily on the vascular co-option, controlled by the expression of the matrix metalloproteinases MMP-2 and MMP-9." (PMID 33466236, 2021). "For example, M6A methyltransferase METTL3 is upregulated in melanoma and modulates melanoma cell invasiveness through MMP2." (PMID 34026852, 2021). "The protein expression of MMP2 in the A375LM3IF4g/Luc and A375LM5IF4g/Luc melanoma cells was higher (4.0- to 3.0-fold, respectively) than the other two parental cell lines." (PMID 33810045, 2021). "STAT3 activity is higher in human brain metastatic cells than in primary melanoma cells, and its activation induces angiogenesis, cell invasion, MMP-2 secretion, cytokine expression, and immune suppression, that contribute to their brain metastatic potential." (PMID 33466236, 2021).
melanoma (continued). "Knockdown of HOTAIR suppresses motility of metastatic melanoma cell lines, which is manifested by decreased gelatinase activity of MMP2 and MMP9." (PMID 34638331, 2021). "B16 melanoma cells that express MMP2 at baseline have slower kinetics in Tlr2–/–Tlr4–/– mice, implicating MMP2 in promoting tumor growth." (PMID 34032639, 2021). "The Laminin5γ2 chain fragmentation by active MT1/MMP and MMP2 is an essential step for aggressive melanoma cells to engage in VM formation." (PMID 33946480, 2021). "Melanoma cells can exert morphological changes in microglia cells, enhancing their proliferation, migratory capacity, and matrix metalloproteinase‐2 (MMP‐2) activation." (PMID 33274599, 2021). "For instance, by mediating MMP2 expression andactivity in melanoma cells, long non-coding RNA (lncRNA) GAS5 represses theinvasion of cancer cells." (PMID 34837683, 2021). "We previously documented that loss of TNX expression accompanies MMP2 and MMP9 upregulation in melanoma tumor cells." (PMID 33782532, 2021). "Plasma levels of CD147/basigin and MMP-2 were also measured before the start of therapy and at disease progression in a small group of melanoma patients treated with vemurafenib or vemurafenib plus cobimetinib." (PMID 33467521, 2021). "CD147-containing microvesicles shed from malignant melanoma cells promote MMP2 expression in recipient fibroblasts." (PMID 32957712, 2020). "Our results showed that MMP2/9-specific inhibitor SB-3CT significantly decreased PD-L1 mRNA and protein levels in melanoma cell lines and significantly reduced the PD-L1 protein level in PD-L1 overexpression cell line." (PMID 32988398, 2020). "According to previous reports, laminarin suppresses proliferation, colony formation, and migration of human melanoma cells by inhibiting matrix metalloproteinase-2 (MMP-2), MMP-9, and the p-ERK1/2 signaling cascade." (PMID 32182828, 2020). "Since active MMP2 was reduced in the conditioned media of melanoma cells, we also investigated the MMP2 expression immunohistochemically." (PMID 33375117, 2020). "Based on our results, we used a miR-152-3p inhibitor to further examine the effects of curcumol on MMP2/9 and E/N-cadherin in mouse melanoma B16 cells." (PMID 32194780, 2020). "In the early-AJCC-staged melanoma group, we exclusively detected in the enriched endothelial fraction E-CMC, MCAM expression, 5′-portion, and both isoforms, associated with VE-CADH, MMP2, and MMP9 (these last genes mostly expressed)." (PMID 32548126, 2020). "It reduced the activity of MMP-2 in the studied melanoma lines by 60% for WM266-4, 50% for Lu1205, and at least about 35% for the WM115 line." (PMID 31586300, 2020). "Expression of metalloproteinase-2 (MMP-2), an enzyme that participates in increasing melanoma invasiveness during development of resistance, was upregulated only in selected resistant cell lines, especially in those derived from DMBC11 drug-naïve cell line." (PMID 31936151, 2020). "To verify SPP1's role in mediating MMP2 expression in melanoma, we knocked down SPP1 in A375 or SK-MEL-28 melanoma cells and found decreased MMP2 expression." (PMID 33052224, 2020). "On the other hand, in melanoma cells, loss of LKB1 promotes cell invasion and migration through upregulation of MMP-2." (PMID 33041669, 2020). "Taken together, the specific inhibition of mTORC2 leads to reduced cell mobility and migration by regulation of MMP2 activity in melanoma cells in vitro." (PMID 33375117, 2020). "Further study showed that shikonin decreased the levels of STAT3-targeted genes Mcl-1, Bcl-2, MMP-2, vimentin, and Twist, which are involved in melanoma survival, migration, and invasion." (PMID 32536866, 2020). "NOX1 is overexpressed in melanoma cells and controls melanoma invasion by regulating matrix metaloproteinase-2 (MMP-2) transcription." (PMID 32850409, 2020).
melanoma (continued). "Based on the TCGA database, we found that Wdfy4, CYBB, Itgb2, and Itgam were down-regulated and MMP2 was up-regulated in melanoma samples compared with normal samples." (PMID 33679872, 2020). "Taken together, the data from this study suggest that OPN increases migration, invasion, and tumor formation in melanoma through activation of MMP-2 by MT1-MMP in an NF-κB dependent manner." (PMID 33203146, 2020). "Previous study has demonstrated that both melanoma cell invasion and matrix metalloproteinase 2 (MMP-2) activity increased and decreased with EIF5A2 overexpression and knockdown, respectively." (PMID 32522053, 2020). "Using the novel mTORC2 specific inhibitor JR-AB2-011, we show significantly reduced migration and invasion capacity by impaired activation of MMP2 in melanoma cells." (PMID 33375117, 2020). "Increased expression of EIF5A2 has been suggested to enhance melanoma cell invasion with increasing MMP-2." (PMID 32605067, 2020). "METTL3 promotes cell invasion and migration and increases MMP2 and N‐cadherin levels in melanoma cells, which are completely reversed in cells transfected with inactivated METTL3 through site mutant." (PMID 33029866, 2020). "In particular, the authors have shown in C918 cells, a model for choroidal malignant melanoma (CMM, an interocular type of melanoma), that both MMP-2/9 transcripts and proteins were downregulated when FOXCUT and/or miR-296 were transfected in C918 cells." (PMID 32392801, 2020). "Overexpression of SPP1 partially reversed MMP2 expression in melanoma cells after BET inhibitor treatment." (PMID 33052224, 2020). "Numerous studies have shown that MMP2/9 expression is regulated by NF-κB signaling pathways in melanoma 31-33, and curcumol induced HSC-T6 cell death via this pathway." (PMID 32194780, 2020). "This MMP is also involved in the invasive phenotype of some tumors, including melanoma, by interacting with MMP-2 in the stroma and promoting cancer progression." (PMID 32392801, 2020). "One of the earliest reports indicates that IL-8, an angiogenic factor, induces MMP-2 expression and activity in melanoma cells, enhancing their invasion." (PMID 31921634, 2019). "We have recently reported that hYSK1 promotes migration of melanoma and fibrosarcoma cells by repressing p16INK4a nuclear translocation via direct interaction, thereby resulting in increased SP-1-mediated MMP2 transcription." (PMID 30646538, 2019). "In tissue homogenate of subcutaneous melanoma excised from NAP-HBTA treated-mice we found a significant reduction of both MMP-2 and MMP-13 proteins compared to control mice." (PMID 30800067, 2019). "For example, TCDD exposure of human A2058 melanoma cells induced the expression of MMP-1, MMP-2, and MMP-9, which was associated with enhanced invasive growth of melanoma cells in vitro." (PMID 31795255, 2019). "Results of studies using tissue microarray, immunohistochemistry of melanoma biopsies of primary and metastatic lesions, as well as nevi, confirmed that MMP-2 is predictive of primary and metastatic stages." (PMID 29492694, 2018). "Inflammatory signals such as TNF and MMP-2 activity are key intrinsic players to determine melanoma cells aggressiveness suggesting new venue sin the identification of novel molecular targets with potential therapeutic relevance." (PMID 30591049, 2018). "The melanoma tissues overexpressing MYOF are prone to form VM channels, and this formation is accompanied by an increase in MMP‐2 secretion and loss of E‐cadherin at adherens junctions." (PMID 29164766, 2018). "In the current study, we found that in two melanoma cell lines, A2058 and A375, uPA, TIMP-1, MMP-2 and MMP-9 were associated with cell migration and invasion." (PMID 30042328, 2018). "In fact, earlier studies from the lab revealed HABP1 induced migration of melanoma cells, as well as tumor growth by NF-κB dependent MMP-2 activation." (PMID 29890947, 2018).